UGT2B28 (UDP glucuronosyltransferase family 2 member B28)
Description:
[Isoform 1]: UDP-glucuronosyltransferase (UGT) that catalyzes phase II biotransformation reactions in which lipophilic substrates are conjugated with glucuronic acid to increase the metabolite's water solubility, thereby facilitating excretion into either the urine or bile. Essential for the elimination and detoxification of drugs, xenobiotics and endogenous compounds. Catalyzes the glucuronidation of endogenous steroid hormones such as androgens (androsterone, 3alpha-androstanediol) and estrogens (estradiol, estrone). Catalyzes the glucuronidation of bile acid substrates, which are natural detergents for dietary lipids absorption. Displays glucuronidation activity toward the phenolic compounds eugenol. [Isoform 2]: Lack UDP-glucuronosyltransferase (UGT) activity.
Tractability: Antibody: UniProt predicts a signal peptide or a membrane-spanning region. PROTAC: ubiquitination databases record sites on it.
Target class: Enzyme; Transferase
Gene: Protein-coding gene on chromosome 4 (69,280,475 to 69,295,050, forward strand). Ensembl gene ENSG00000135226.
Subcellular location: Endoplasmic reticulum membrane; Cytoplasm, perinuclear region
Pathways (Reactome):
Drug ADME: Aspirin ADME
Metabolism: Glucuronidation
Gene Ontology:
Molecular function: glucuronosyltransferase activity; UDP-glycosyltransferase activity
Biological process: steroid metabolic process; estrogen metabolic process
Cellular component: endoplasmic reticulum; endoplasmic reticulum membrane; nuclear outer membrane; perinuclear region of cytoplasm
Genetic constraint (gnomAD): Loss-of-function variants: 44 observed, 38.8 expected, observed/expected ratio (o/e) 1.13, 90% interval 0.89 to 1.46. The upper end of that interval is the gene's LOEUF score, 1.46, which puts it in group 6 of 6, group 1 being the genes least tolerant of losing a copy. Missense variants: 632 observed, 578.03 expected, observed/expected ratio (o/e) 1.09, 90% interval 1.02 to 1.17. Synonymous variants: 199 observed, 191.71 expected, observed/expected ratio (o/e) 1.04, 90% interval 0.92 to 1.17.
Homologues: Orthologues: zebrafish ugt2a7 (50% identical), zebrafish ugt2b1 (48% identical), zebrafish ugt2b5 (48% identical), zebrafish ugt5a1 (40% identical), zebrafish ugt5a2 (40% identical), zebrafish si:ch73-334d15.1 (39% identical), zebrafish ugt5c1 (38% identical), zebrafish ugt5b4 (38% identical), zebrafish ugt5g1 (38% identical), zebrafish ugt5c3 (37% identical), zebrafish ugt5f1 (37% identical), zebrafish ugt5b2 (37% identical), and 93 more. Paralogues in human: UGT2B11 (95% identical), UGT2B10 (89% identical), UGT2B7 (85% identical), UGT2B4 (84% identical), UGT2B15 (76% identical), UGT2B17 (75% identical), UGT2A2 (58% identical), UGT2A3 (58% identical), UGT2A1 (50% identical), UGT1A10 (42% identical), UGT1A8 (42% identical), UGT1A1 (42% identical), and 9 more.
Diseases named in the same sentence as UGT2B28 in open-access papers:
UGT2B28 is named in the same sentence as 18 diseases in open-access papers, as found by Europe PMC text mining. Sharing a sentence is not in itself a finding about the gene and the disease. The quoted sentences say what the papers report.
prostate carcinoma (9 papers, 2017 to 2025). A carcinoma that arises from epithelial cells of the prostate gland. "Complete deletions and differential expression of the human glycosyltransferase UGT2B17 and UGT2B28 genes are linked to prostate cancer (PCa) risk and progression, leukaemia, autoimmune and other diseases." (PMID 36347965, 2023). "UGT2B17 and UGT2B28 germline deletions and differential expression have been associated with a number of clinical conditions such as risk and progression of prostate cancer (PCa), but also leukaemia, oesophageal, colorectal, lung, bladder and breast cancers." (PMID 36347965, 2023). "Functional glucuronidation assays support that the pregnanediol derivatives 5α-pregnan-3α,20α-diol and 5α-pregnan-3β,20α-diol are conjugated by UGT2B28 in LNCaP prostate cancer cells." (PMID 36347965, 2023). "In primary prostate cancer, if androgen expression is elevated, UGT2B28 expression is also elevated, therefore, UGT2B28 can be a good predictor of prostate cancer." (PMID 36741721, 2022). "UGT2B28 is a key member of this group of UGTs whose mechanistic role in prostate cancer remains uncharacterized." (PMID 35954173, 2022). "The UGT2B28 enzymes have been shown to be expressed in human testis, prostate, and prostate cancer cell line, LNCaP, where they conjugate 5α-androstane-3α,17β-diol, 5β-androstane-3α,17β-diol and androsterone, and testosterone." (PMID 28673330, 2017). "In support of this notion, a recent study highlighted a mechanism by which the interaction of UGT2B28 with the adaptor huntingtin interacting protein 1 triggered epidermal growth factor receptor signaling to promote prostate cancer cell proliferation and invasion." (PMID 37174695, 2023). "Elevated circulating testosterone has been associated with UGT2B28 nuclear staining which may decrease expression of UGT2B15 and UGT2B17 since studies show that their expression is elevated in patients and prostate cancer cell cultures treated with antiandrogens." (PMID 28673330, 2017).
osteoporosis (2 papers, 2017 to 2025). A condition of reduced bone mass, with decreased cortical thickness and a decrease in the number and size of the trabeculae of cancellous bone (but normal chemical composition), resulting in increased fracture incidence. "Polymorphic deletions were detected in UGT2B17 and UGT2B28 and segmental duplications were found near these genes, which were associated with osteoporosis risk related to the occurrence of NAHR caused by segmental duplications." (PMID 28403820, 2017). "The metabolic profiles of UGT2B17-deficient men and UGT2B28-deficient women were most impacted, with UGT2B17 deficiency affecting various metabolites linked to metabolic diseases, arthritis, and osteoporosis." (PMID 40264209, 2025). "For the UGT2B17 and UGT2B28 enzymes, the absence of their genes is not lethal; however, an increasing number of studies have found that differences in their expression patterns and/or deletions are associated with osteoporosis, autoimmune diseases and cancers." (PMID 40264209, 2025).
prostate tumor (2 papers, 2020 to 2022). "Taken together, our findings demonstrate a key role for the UGT2B28 gene in promoting prostate tumor growth." (PMID 35954173, 2022). "Similar to normal prostate tissue, prostate tumours expressed several UGT2B mRNAs, including UGT2B17 but also UGT2B4, UGT2B7, UGT2B10, UGT2B11, UGT2B15 and UGT2B28." (PMID 32047296, 2020).
Autoimmunity (1 paper, 2025). The occurrence of an immune reaction against the organism's own cells or tissues. "The UGT2B28 single-copy state (CN = 1) was enriched in cases but is also relatively common in the general population, and the locus overlaps the UGT2B17 region, so specificity for autoimmunity remains uncertain." (PMID 41465179, 2025).
breast carcinoma (1 paper, 2022). "In contrast, the breast cancer ZR751 cell line had three mutations in UGT2B28 [c.357_358delinsAT (Phe119_His120delinsLeuTyr); c.357T > A (Phe119Leu); c.358C > T (His120Tyr)]." (PMID 36428799, 2022). "For example, UGT2B28 is highly upregulated upon androgen exposure in the ZR751 breast cancer cell line, which would suggest that it is a suitable line to study the biological function of this gene in breast cancer." (PMID 36428799, 2022).
chronic hepatitis B (1 paper, 2019). "It was found that viral etiology (chronic hepatitis B, C) and the UGT2B28 rs2132039 genomic variant were independently associated with the age (all adjusted P < 0.05)." (PMID 31805979, 2019). "A univariate-multivariate analysis showed that viral etiology (chronic hepatitis B, C) and the UDP glucuronosyltransferase family 2 member B28 (UGT2B28) genomic variant rs2132039 were independently associated with the age at presentation of HCC (all adjusted P < 0.05)." (PMID 31805979, 2019). "The genomic variant UGT2B28-rs2132039 and an adjacent copy number variation CNP605 have recently been reported to be associated with the natural history of chronic hepatitis B, particularly the e-antigen seroconversion." (PMID 31805979, 2019).
diabetes (1 paper, 2025). "UGT2B28 KO females exhibited higher levels of fructose as well as N-lactoyl-phenylalanine, an amino acid derivative, indicative of mitochondrial dysfunction that is prevalent in plasma of individuals experiencing septic shock or with certain health conditions such as diabetes (Padj<0.05)." (PMID 40264209, 2025).
metastatic disease (1 paper, 2022). "Here, we identified a higher expression of the metabolic enzyme UGT2B28 in localized PCa and metastatic disease compared to benign adjacent tissue, in AA PCa compared to benign adjacent tissue, and in AA PCa compared to European American (EA) PCa." (PMID 35954173, 2022). "Immunohistochemical staining of UGT2B28 protein expression in a TMA containing tissues from benign prostate, localized tumors, and metastatic tumors, revealed an increase in UGT2B28 expression in localized tumors vs. benign adjacent prostate tissue and metastatic vs. localized tumors." (PMID 35954173, 2022).
metastatic prostate carcinoma (1 paper, 2021). A carcinoma that arises from the prostate gland and has spread to other anatomic sites. "For example, previous work shows that UGT2B17 and UGT2B28 are overexpressed in advanced and metastatic prostate cancer and associate with poor outcomes." (PMID 34503303, 2021).
tumor (4 papers, 2015 to 2022). "To test whether the UGT2B28-associated tumor growth was reliant on AR signaling, we subcutaneously injected VCaP NT, UGT2B28 KD, and UGT2B28 R cells in castrated mice." (PMID 35954173, 2022). "Moreover, in the same study, we found UGT2B28 expression to be associated with PCa progression, which characterized its tumor promoting role." (PMID 35954173, 2022). "We previously determined that UDP-glucuronic acid, the co-substrate of UGT2B28, is a precursor for hyaluronic acid and the depletion of this precursor reduces tumor growth." (PMID 35954173, 2022). "Specifically, even in the castrated setting, the KD tumors had a significantly delayed tumor take and reduced tumor growth rate, compared to control and UGT2B28 R tumors." (PMID 35954173, 2022). "Multiple UGT family members were identified, including UGT2B28, a member that has been reported to be associated with early biochemical recurrence but not characterized to date for its tumor promoting function." (PMID 35954173, 2022). "In contrast, the UGT2B28 KD cells across the three models exhibited a significant delay (an additional 2–11 days) in tumor take rates, with the palpable tumors appearing on Days 10, 14, and 32 post-injection in the LNCaP, LAPC-4 and VCaP xenograft models, respectively." (PMID 35954173, 2022). "It is possible that an altered balance between HAS2 and HYAL1 upon UGT2B28 KD may contribute to the delay in tumor take and tumor growth, which would need to be verified in the future using additional experiments." (PMID 35954173, 2022). "Given the regulation of UGT2B28 expression by AR, we sought to determine whether the organoid formation and tumor growth phenotypes that we observed in AD cell lines in response to UGT2B28 manipulation were dependent on androgen-bound AR signaling." (PMID 35954173, 2022). "Importantly, both the tumor take and tumor growth rate were completely rescued in all three xenograft models upon the re-expression of UGT2B28 (UGT2B28 R)." (PMID 35954173, 2022). "Next, we examined the role of UGT2B28 on tumor growth in vivo." (PMID 35954173, 2022). "However, our in vitro and in vivo functional data revealed similar effects on 3D organoid formation and a reduction in tumor growth upon UGT2B28 KD, both in a ligand-driven and castrated AR signaling environment, which suggests that UGT2B28 may have non-canonical roles in prostate tumorigenesis." (PMID 35954173, 2022). "It is particularly interesting that our results show that UGT2B28 is regulated by AR and AR-v7 at the genetic level, and its tumor promoting role is not fully compromised by castrated mouse models or the ablation of AR or androgens." (PMID 35954173, 2022).
cancer (3 papers, 2020 to 2024). A tumor composed of atypical neoplastic, often pleomorphic cells that invade other tissues. "We further analyzed UGT2B15, UGT2B17, and UGT2B28 to determine whether they were genetically linked to cancer." (PMID 39457450, 2024). "Building on these observations and given their wide tissue distribution, we hypothesised that UGT2B17 and UGT2B28 deficiencies induce a significant rewiring of the systemic metabolome to which cancer cells are exposed, driven by several tissues." (PMID 36347965, 2023).
cardiovascular diseases (1 paper, 2025). "Higher levels of fructose, which was one of the metabolites most enriched in plasma samples from UGT2B28 KO females, were also associated with an increased risk of cardiovascular diseases." (PMID 40264209, 2025).
metabolic disorders (1 paper, 2025). "Metabolites impacted by a UGT2B28 deficiency such as amino acids, were linked to metabolic disorders in women." (PMID 40264209, 2025). "In the case of UGT2B28-deficient individuals, the highly impacted fatty acids and amino-acid derivatives in women were closely associated with several metabolic disorders, an unexpected finding that opens a novel avenue of investigation regarding UGT2B28 function." (PMID 40264209, 2025).
UGT2B28 also shares sentences with these, for which no sentence is quoted: Arthritis (1 paper); hepatocellular carcinoma (1); Hypertension (1); leukaemia (1); Obesity (1).